LDHB (lactate dehydrogenase B)
Diseases named in the same sentence as LDHB in open-access papers (continued):
Sharing a sentence is not in itself a finding about the gene and the disease.
colorectal cancer (continued). "SIRT5 can mediate the deacetylation of lactate dehydrogenase B (LDHB) thus promoting autophagy and tumorigenesis in colorectal cancer." (PMID 39479446, 2024). "Furthermore, LDHB expression is elevated in different types of tumors, such as triple-negative breast cancer, thyroid cancer, laryngeal squamous cell carcinoma, lung adenocarcinoma, bladder transitional cell carcinoma, osteosarcoma, testicular germ cell tumor and colorectal cancer." (PMID 35669414, 2022). "We performed IHC and scored the results in TMA consisting of 79 patients with stage I-III colorectal cancer and corresponding adjacent normal tissues (ANT) to test the expression status of RPS7, HIF-1α, GLUT4 and LDHB." (PMID 26735579, 2016). "Similarly, in colorectal cancer, MSI-H tumors are characterized by SIRT5/LDHB-dependent metabolic control, while MSS tumors show stronger regulation by chromatin modifiers such as SIRT1 and SIRT7." (PMID 41213956, 2025). "In this study, we demonstrate that RPS7 inhibits the colorectal cancer (CRC) cell glycolysis by suppressing the expression of hypoxia-inducible transcription factor-1α (HIF-1α) and the metabolic promoting proteins glucose transporter 4 (GLUT4) and lactate dehydrogenase B (LDHB)." (PMID 26735579, 2016). "Taken together, our data revealed the negative correlation between RPS7 and HIF-1α, and they modulate the glycolysis of colorectal cancer through molecules including GLUT4 and LDHB, which may represent novel prognostic markers and/or therapeutic targets for colorectal cancer." (PMID 26735579, 2016).
lung carcinoma (19 papers, 2011 to 2025). "A previous analysis of a cohort of 540 lung cancer patients from the TCGA database showed that high LDHB expression was associated with shorter survival." (PMID 40090955, 2025). "In summary, in vitro LDHB silencing in lung cancer cells decreases nucleotide metabolism, which is associated with increased DNA damage accumulation." (PMID 40158058, 2025). "In addition, high LDHB expression was significantly associated with shorter overall survival and median survival in 65 lung cancer patients who had received radiotherapy." (PMID 40090955, 2025). "Silencing LDHB in lung cancer cells has been shown to reduce invasion and migration capabilities, likely due to decreased intracellular glutathione levels and altered mitochondrial metabolism." (PMID 41154605, 2025). "The differential expression patterns of LDHA and LDHB in lung cancer suggest their potential as prognostic biomarkers." (PMID 41154605, 2025). "This highlights LDHB’s role in maintaining lung cancer cells’ redox balance and metastatic potential." (PMID 41154605, 2025). "We described before that LDHB is required for plasma membrane-localized SLC7A11-mediated glutathione metabolism in the tested KRAS-mutant lung cancer cells." (PMID 40090955, 2025). "Our group previously identified two FDA-approved anticancer drugs, tucatinib and capmatinib, originally developed for the treatment of breast and lung cancers, as uncompetitive inhibitors of LDHB." (PMID 40733189, 2025). "Increasing evidence suggests that LDHB is critical for malignant progression in triple-negative breast cancer, K-Ras amplified lung cancer and colon cancer." (PMID 35669414, 2022). "LDHB is upregulated in lung cancer cell lines that are characterized by RAS pathway activation and it is required for the in vivo KRAS-mutant lung tumors growth." (PMID 31035592, 2019). "High levels of LDHB are also observed in other lung cancer subtypes, especially in those driven by c-MET (2/2 examined cell lines) and EGFR (3/8 tested cell lines)." (PMID 31035592, 2019). "The elevated LDHB level in serum was validated to correlate with clinical stage and poor outcome of lung cancer, indicating its potential to predict prognosis in lung cancer patients." (PMID 31448219, 2019). "Meanwhile, elevated LDHB levels in lung adenocarcinoma tissues are significantly associated with poor prognosis and reduced survival rates in cancer patients with KRAS-wild-type lung cancer." (PMID 41154605, 2025). "LDHA and LDHB subunits play pivotal roles in the metabolic reprogramming of lung cancer cells." (PMID 41154605, 2025). "While LDHA has been extensively studied as a therapeutic target, particularly in cancer, due to its role in the Warburg effect, LDHB remains underexplored, despite its involvement in the metabolic reprogramming of specific cancer types, including breast and lung cancers." (PMID 40733189, 2025). "We found that silencing of LDHB in lung cancer cells resulted in only modest induction of apoptosis, which thus could not fully account for the significant loss of viability, sphere, and colony formation." (PMID 40090955, 2025). "Indeed, we have previously shown that silencing LDHB expression reduced tumorigenesis and tumor growth in lung cancer." (PMID 40790017, 2025). "To test whether targeting LDHB also sensitizes cancer cells to radiotherapy in vivo, we treated human lung cancer xenograft tumors and orthotopic lung tumors with local radiotherapy." (PMID 40090955, 2025).
lung carcinoma (continued). "We reported previously that silencing LDHB in KRAS-mutant lung cancer cell lines significantly reduced the expression of SLC7A1111, which is required for oncogenic RAS transformation and encodes a plasma membrane-localized cystine/glutamate antiporter that provides cysteine for GSH synthesis." (PMID 40090955, 2025). "LDHB was highly expressed in lung cancer tissues but low in kidney and thyroid cancer tissues." (PMID 38291366, 2024). "Lactate dehydrogenase B in serum was shown to be correlated with the clinical stage of lung cancer." (PMID 29465809, 2018). "The level of LDHB also could be used to distinguish lung cancer from benign lung disease or healthy control groups with a sensitivity of 81%, a specificity of 70%, and a total accuracy of 76%." (PMID 22363243, 2011). "In addition, we recently showed that targeting LDHB sensitizes lung cancer cells to radiotherapy." (PMID 40790017, 2025). "It suggests that targeting LDHB may provide a broad therapeutic option for patients with lung cancer that specifically overexpress LDHB, especially given that high LDHB expression is considered as a significant predictor of shorter survival rate in patients suffering from lung adenocarcinomas." (PMID 31035592, 2019). "This is in agreement with our previous study, which revealed that LDHB silencing similarly did not elevate ROS levels in lung cancer cells." (PMID 40790017, 2025). "Although this model explains the metabolic phenotypes in several cancers, such as liver, brain, and pancreatic cancer, it is not supported by clinical data from colon, breast, and lung cancers, in which LDHB is also abundant." (PMID 31804482, 2019).
leukemia (17 papers, 2020 to 2025). A malignant (clonal) hematologic disorder, involving hematopoietic stem cells and characterized by the presence of primitive or atypical myeloid or lymphoid cells in the bone marrow and the blood. "Further studies should focus on the underlying leukaemia‐promoting mechanisms and investigate LDHB as a therapeutic target." (PMID 32391634, 2020). "The FTO/PFKP/LDHB axis has been shown to be involved in glycolysis in leukemia via m6A modification." (PMID 41373022, 2025). "For instance, YTHDF2 accelerates decay of GLUT4 mRNA in BRCA,253 while facilitates expression of PFKP and LDHB in leukemia, leading to opposite effects." (PMID 38531882, 2024). "It attenuates aerobic glycolysis and downregulates the expression of FTO/LDHB/PFKP in leukemia cells." (PMID 35186927, 2022). "R-2-hydroxyglutarate mediated anti-leukemia activity partly through LDHB inhibition in primary patient samples, supporting the inhibition of LDHB as a potential treatment for most cancer." (PMID 36407005, 2022). "It was reported that knocking down FTO or LDHB (lactate dehydrogenase B) inhibits R-2HG in leukemia cells." (PMID 35186927, 2022). "On the other hand, 2-HG attenuates aerobic glycolysis in leukemia by targeting the FTO/m6A/PFKP/LDHB axis." (PMID 34516556, 2021). "Additionally, one study revealed that R-2HG attenuated aerobic glycolysis in leukemia by targeting the FTO/m6A/PFKP/LDHB axis." (PMID 41373022, 2025). "Thus, 2HG has been shown to inhibit the post-transcriptional upregulation of the platelet isoform of PFK1 (PFKP) and the B isoform of LDHB (LDHB) in leukemia cells, thereby suppressing aerobic glycolysis." (PMID 40801609, 2025). "In addition, the FTO/m6A/PFKP/LDHB axis is targeted by R-2-hydroxyglutarate, resulting in the suppression of aerobic glycolysis in leukemia." (PMID 37858219, 2023). "PFKP and LDHB play an important role in glycolysis and tumorigenesis of leukemia." (PMID 35590394, 2022). "In a study where R-2HG was shown to attenuate aerobic glycolysis in leukemia by targeting the FTO/m6A/PFKP/LDHB axis, it was found that PFKP promotes glycolysis and exerts an oncogenic role in leukemia." (PMID 39820532, 2025). "R-2HG can block the post-transcriptional upregulation of PFKP and LDHB mediated by FTO/m6A, thus attenuating aerobic glycolysis in sensitive(IDH-wildtype) leukemic cells and inhibiting the occurrence of leukemia." (PMID 35590394, 2022). "In R-2HG-sensitive leukemia cells, R-2HG suppresses FTO activity and decreases the stability of target mRNA phosphofructokinase platelet (PFKP) and lactate dehydrogenase B (LDHB) by YTHDF2." (PMID 35864970, 2022). "Scholars have reported that R-2-hydroxyglutarate (R-2HG) abates FTO/m6A/YTHDF2-mediated upregulation of phosphofructokinase platelet (PFKP) and lactate dehydrogenase B (LDHB) which suppress aerobic glycolysis and exert an anti-tumor effect in R-2HG-sensitive leukemia cells." (PMID 36035161, 2022). "LDHB regulates mitochondrial respiration in leukemia but not in normal hematopoietic cells, also indicating the regulatory potential of redox state." (PMID 36407005, 2022). "Moreover, a recent study found that R-2HG also suppresses glycolysis in leukemia cells by abrogating FTO/m6A/YTHDF2-mediated upregulation of two critical glycolytic genes phosphofructokinase platelet (PFKP) and lactate dehydrogenase B (LDHB)." (PMID 34485297, 2021).
pancreatic cancer (17 papers, 2015 to 2026). "Reduced LDHB expression via promoter hypermethylation has been observed in prostate, breast, and pancreatic cancers, and greater LDHB suppression is associated with metastatic progression, particularly in hypoxia." (PMID 37107600, 2023). "In this study, we demonstrated that a high LDHB level is associated with poor prognosis in pancreatic cancer." (PMID 30419950, 2018). "Conversely, a recent study indicated that positive LDHB protein expression was associated with progression and poor prognosis in patients with pancreatic cancer." (PMID 30419950, 2018). "Methylation of the telomerase reverse transcriptase (TERT) promoter and regulation of telomerase by lactate dehydrogenase B (LDHB) is the mechanism of telomerase reactivation in pancreatic cancer." (PMID 38594465, 2024). "The team also found that LDHB was negatively correlated with the disease-free survival (DFS) of patients by detecting pancreatic cancer tissue and adjacent positive tissue." (PMID 38594465, 2024). "Aside from driving glycolysis, LDHB has also been found to induce pancreatic cancer cell immortalization by activating telomerase." (PMID 39213172, 2024). "Hypermethylation of the LDHB promoter region has been reported in several types of cancer, including gastric cancer, hepatocellular carcinoma, and pancreatic cancer." (PMID 37547725, 2023). "Higher LDHB expression was detected in pancreatic cancer tissues compared with that in adjacent normal tissues and expression of LDHB correlated negatively with prognosis." (PMID 35669414, 2022). "Our in vitro experiments showed that knockdown of LDHB inhibited the growth of pancreatic cancer cells." (PMID 35669414, 2022). "The downregulation of LDHB is an early event in the development of breast, prostate, and pancreatic cancer and is correlated with high proliferation, increased tumor cell invasion, and unfavorable survival outcomes." (PMID 36698888, 2022). "High expression of LDHB correlated negatively with the overall survival of pancreatic cancer patients." (PMID 35669414, 2022). "Our findings indicated that LDHB is elevated in pancreatic cancers and correlated negatively with the overall survival of pancreatic cancer patients, which is consistent with the RNA-seq data and reported results." (PMID 35669414, 2022). "LDHB expression was elevated in pancreatic cancer tissues and correlated negatively with overall survival of patients." (PMID 35669414, 2022). "To explore the clinical significance of LDHB in pancreatic cancer, we performed IHC to determine LDHB protein expression in 50 pairs of pancreatic cancer and matched adjacent normal tissues." (PMID 35669414, 2022). "Relative telomere length was measured in pancreatic cancer cells with transient knockdown of LDHB and long-term knockdown of LDHB by qPCR." (PMID 35669414, 2022). "The results showed that the interaction of TERT and TERC decreased after knockdown of LDHB, which suggested that LDHB regulates telomerase activity in pancreatic cancer cells by affecting the assembly of TERT and TERC." (PMID 35669414, 2022). "In this study, we investigated the potential relation with metabolic enzymes and telomerase activity in pancreatic cancer and identified that LDHB interacted with TERT and regulated telomerase activity independent of its metabolism regulating function." (PMID 35669414, 2022). "Although the role of LDHB in macrophages is underappreciated, in pancreatic cancer a low LDHB expression induces glycolysis." (PMID 34158867, 2021). "The results of a survival analysis indicated that high expression levels of both LAT2 and LDHB predicted a poor prognosis in patients with pancreatic cancer." (PMID 30419950, 2018). "(B, C) The expression level of LDHB in 69 pancreatic cancer tissue samples was higher than that in the matched paracancerous tissues (*, P < 0.05)." (PMID 30419950, 2018).
pancreatic cancer (continued). "We found that the expression levels of both LAT2 and LDHB in pancreatic cancer tissues were higher than those in the paracancerous tissues and that high levels of both LAT2 and LDHB were associated with poor prognosis." (PMID 30419950, 2018). "We also investigated the correlation between the LDHB expression level and the prognosis of pancreatic cancer." (PMID 30419950, 2018). "Then, we detected the expression level of LDHB in 87 pancreatic cancer tissue samples and 71 matched paracancerous tissues using IHC, with two cases of IHC failure." (PMID 30419950, 2018). "Similarly, silencing of LDHB reduced the growth of some cancer cell lines, whereas glycolysis was promoted in pancreatic cancer cells, resulting in increased proliferation, invasion, and migration in hypoxia." (PMID 40790017, 2025). "Compared with adjacent normal tissues, pancreatic cancer tissues expressed higher levels of LDHB." (PMID 35669414, 2022). "Thus, we identified LDHB as the first glucose metabolic enzyme contributing to telomerase activity and pancreatic cancer cell immortalization." (PMID 35669414, 2022). "However, contradictory results have been reported that LDHB expression was reduced in pancreatic cancer tissues compared to normal tissues and inhibition of LDHB promotes pancreatic cancer progression under hypoxia via inducing glycolytic phenotype." (PMID 35669414, 2022). "Furthermore, LDHB suppression due to promoter hypermethylation has already been shown to induce a glycolytic transition in pancreatic cancer." (PMID 34158867, 2021). "In addition, protein levels of lactate dehydrogenase protein isoforms A and B (LDHA, LDHB), key enzymes participating in glucose metabolism and overexpressed in pancreatic cancer were highly expressed in ML and severely down regulated in HS." (PMID 32228510, 2020). "Mechanistically, LAT2 could regulate the glutamine/p-mTORSer2448/glutamine synthetase feedback loop to keep mTOR activated and to upregulate LDHB in order to activate glycolysis, thereby promoting chemoresistance in pancreatic cancer cells." (PMID 30419950, 2018). "Similarly, reduced LDHB expression levels have also been observed in several cancer types, such as prostate cancer and pancreatic cancer." (PMID 30441870, 2018). "Therefore, we speculate that targeting LDHB may present a new avenue for pancreatic cancer treatment." (PMID 35669414, 2022). "However, the expression and function of LDHB in pancreatic cancer remains largely unclear." (PMID 35669414, 2022). "In addition, high levels of both LAT2 and LDHB are poor prognostic predictors in pancreatic cancer." (PMID 30419950, 2018). "In this context, we recently demonstrated that LDHB silencing sensitizes not only NSCLC, fibrosarcoma, and pancreatic cancer cells but also MSTO-211H cells, i.e., a biphasic PM cell line, to ferroptosis induction." (PMID 40790017, 2025). "Herein, the overexpression of DLEU2L in pancreatic cancer cells successfully downregulated the expression of GLUT1, LDHB, HK2, and PKM2, which are positive regulators of the Warburg effect." (PMID 33968986, 2021). "(D, E) Kaplan-Meier survival analysis indicated that the overall survival rate of the high-LDHB and high-LAT2 level group is poorer than that of pancreatic cancer patients with other LDHB and LAT2 statuses (P = 0.0044)." (PMID 30419950, 2018). "To assess whether inhibiting lactylation could suppress neural invasion in pancreatic cancer, we decreased global lactylation in PANC-1 cells by transfecting siRNAs targeting LDHA and LDHB." (PMID 41356184, 2026). "As for LDHB, Wang observed that LDHB expression was higher in pancreatic cancer tissues using IHC analysis, and its expression was negatively correlated with prognosis (OS) in 50 pancreatic cancer patients." (PMID 37547725, 2023).
pancreatic cancer (continued). "Consistent with previous findings concerning prostate and pancreatic cancer, our results suggested a significantly lower level of LDHB expression in HCC tissue samples than in noncancerous tissue samples." (PMID 26426634, 2015). "Then, the upregulated LDHB could activate glycolysis and decrease GEM sensitivity in pancreatic cancer, and the increased glutamine synthetase and decreased glutaminase could further increase the level of intracellular glutamine, which is indispensable for mTOR activation." (PMID 30419950, 2018).